YAP1 (Yes1 associated transcriptional regulator)
Diseases named in the same sentence as YAP1 in open-access papers (continued):
Sharing a sentence is not in itself a finding about the gene and the disease.
pancreatic adenocarcinoma (15 papers, 2018 to 2025). "First, we performed a cBioportal analysis of the correlation of PAF1 with YAP1 in the pancreatic adenocarcinoma (QCMG, Nature 2016) dataset." (PMID 36180487, 2022). "Nevertheless, these two databases consistently revealed that that YAP1 was highly expressed in lymphoma and pancreatic adenocarcinoma (PAAD)." (PMID 34257617, 2021). "Survival analysis showed that NMU/Col1a1/YAP1 expression was associated with poor overall survival, and NMU expression was the highest in pancreatic adenocarcinoma patients with pancreatitis in TCGA." (PMID 31575084, 2019). "The expression levels of CTNNB1, RELA, TWIST1, and YAP1 in pancreatic adenocarcinoma (PAAD) tissues were higher than those in corresponding normal tissues." (PMID 40124511, 2025). "Our study revealed the significant prognostic potential of YAP1 in adrenocortical carcinoma (ACC), brain Lower Grade Glioma (LGG), and pancreatic adenocarcinoma (PAAD)." (PMID 34257617, 2021).
head and neck cancer (14 papers, 2016 to 2024). A primary or metastatic malignant neoplasm affecting the head and neck. "In head and neck cancer, the mutated Ras oncogene stabilizes YAP1 activity to promote Axl-mediated cell invasion in vitro and metastasis in vivo." (PMID 38673795, 2024). "However, this miRNA was recently identified to inhibit EMT via negatively regulating Yes1-associated transcriptional regulator (YAP1) in head and neck cancer cells." (PMID 33066509, 2020). "HRAS mutations have the ability to trigger YAP1-AXL signaling, leading to metastasis in head and neck cancer." (PMID 38933262, 2024). "The Hippo-YAP1 pathway is oncogenic in head and neck cancer (Santos-de Frutos, Segrelles & Lorz, 2019)." (PMID 33024622, 2020). "YAP1 protein expression was evaluated using IHC in head and neck carcinoma tissues and tumor-adjacent normal tissues." (PMID 31413738, 2019). "In the context of radiotherapy, YAP1 expression was predictive of radio-resistance in patients with head and neck cancer." (PMID 26716514, 2016). "The functional loss of mutated FAT1 has also been reported to be associated with YAP1 activation in head and neck cancer, however, no enrichment of FAT1 mutation was seen among the YAP1-dependent nor WWTR1-dependent models in this study." (PMID 32990596, 2020). "Consistent with previous reports 17, 18, our results showed that YAP1 expression was significantly upregulated in head and neck carcinoma tissues compared to that in tumor-adjacent normal tissues, suggesting that YAP1 overexpression is involved in HNSCC tumorigenesis." (PMID 31413738, 2019). "The cBioPortal online analysis tool (cBioPortal for Cancer Genomics) 16 shows that YAP1 is frequently altered in different types of cancers according to data in The Cancer Genome Atlas (TCGA) database and head and neck carcinoma exhibits the second highest frequency of YAP1 gene alteration." (PMID 31413738, 2019).
hepatoblastoma (13 papers, 2016 to 2025). Hepatoblastoma (HB) is a malignant hepatic tumor and is the most common pediatric liver cancer. "Wnt/β-catenin is known to act in concert with the Yes-associated protein 1 (Yap1) pathway to induce the development of hepatoblastoma." (PMID 36209041, 2022). "Increasing number of studies has shown the cooperation between β-catenin and Yes-associated protein 1 (YAP1) in inducing the development of hepatoblastoma." (PMID 31511432, 2019). "Functional experiments using Hep3B and Huh7 HCC cell lines and HepG2 hepatoblastoma cell line showed that forced YAP1 overexpression was associated with a significant increase in the viability and mRNA levels of the stem cell markers CD133, NANOG, and OCT-3/4 in the three cell lines." (PMID 27359056, 2016). "Mouse models of hepatoblastoma have demonstrated that CTNNB1 point mutations, in combination with the YAP1 oncogene, result in a more differentiated tumor phenotype than that of CTNNB1 exon 3–deletion mutant." (PMID 40684183, 2025). "Reduced LATS2 expression promotes hepatoblastoma progression by inhibiting ferroptosis through the YAP1/ATF4/PSAT1 axis." (PMID 39247829, 2024). "The dysregulated downstream effector molecule of Hippo signaling, YAP1, is involved in hepatoblastoma tumorigenesis." (PMID 37414763, 2023). "Combination of the activated form of YAP1 (YAPS127A) with either hepatoblastoma relevant NFE2L2 mutant or CTNNB1 mutant promotes liver tumorigenesis although either alone is unable to transform normal liver cells in these mouse models." (PMID 37414763, 2023). "We used the SB-HTVI system to induce hepatoblastoma tumor formation driven by mutant Yap1-S127A and β-catenin-ΔN90 in 5-week old FVB mice." (PMID 30863496, 2019). "It was reported that YAP1 co-activated transcription with β-catenin and inhibition of β-catenin led to the inactivation of YAP1 and reduced cellular proliferation in human hepatoblastoma samples." (PMID 31547193, 2019). "Accordingly, it is proposed that β-catenin and YAP-1 interact physically to induce the development of hepatoblastoma." (PMID 31511432, 2019). "Combined β-catenin and YAP1 silencing impairs the growth of human hepatoblastoma cells, while constitutively activated β-catenin and YAP1 trigger liver tumor development in mice." (PMID 27835600, 2016). "However, the role of YAP1 in hepatoblastoma has been minimally studied, and its impact on metabolic reprogramming in hepatoblastoma cells requires in-depth research." (PMID 40303290, 2025). "Importantly, YAP1 activation in conjunction with active-β-catenin yielded hepatoblastoma in the SB-HDTVI model." (PMID 39273023, 2024). "Additionally, NAT10 was primarily positively regulated by the upstream YAP1 signaling pathway and activated PPP, thereby influencing the metabolic reprogramming in hepatoblastoma, further promoting cancer cell proliferation, invasion, and metastasis." (PMID 40303290, 2025). "The interaction between β-catenin and YAP-1 protein may activate mTOR pathway to increase the expression of amino acid transporter, i.e. SLC38A1, which may be critical in the development of hepatoblastoma." (PMID 31511432, 2019). "In a clinical study, the nuclear co-localization of β-catenin and YAP1 was identified selectively in approximately 80% of the cases of hepatoblastoma, but not in hepatocellular carcinoma and cholangiocarcinoma." (PMID 31511432, 2019). "The activation of β-catenin signaling may trigger the activation of other signaling pathways to induce the development of hepatoblastoma, which may include inhibition of TNF-α-dependent apoptosis, increase in the secretion of epithelial growth factor and formation of complex of with YAP-1 protein." (PMID 31511432, 2019).
hepatoblastoma (continued). "The activation of β-catenin signaling may trigger the activation of other signaling pathways to induce the development of hepatoblastoma, including inhibition of TNF-α-dependent apoptosis, increase in the secretion of epithelial growth factor and formation of complex of with YAP-1 protein." (PMID 31511432, 2019).
neuroblastoma (13 papers, 2019 to 2026). Neuroblastoma (NB) is the most common solid, extracranial childhood tumor. "This study demonstrated that YAP‐1 can significantly outperform existing risk variables in predicting neuroblastoma patient survival expectancy." (PMID 38925618, 2024). "YAP‐1 expression in neuroblastoma is associated with significantly poorer survival probabilities and should be considered as a potential therapeutic target." (PMID 38925618, 2024). "In summary, neuroendocrine lineage transcription patterns are highly predictive of prognosis in neuroblastoma, and YAP‐1 evaluation may contribute to a more accurate characterization of recurrence risk in neuroblastoma patients." (PMID 38925618, 2024). "RNA-sequencing detected YAP1-dependent gene signatures in Tet-ON SK-N-AS and SH-EP neuroblastoma cell models expressing wildtype YAP1 or constitutively activated YAP1S127A." (PMID 41681855, 2026). "YAP1 depletion sensitizes neuroblastoma to trametinib, and overexpression of YAP1 induces trametinib resistance in neuroblastoma cells." (PMID 38169595, 2024). "YAP‐1 expression has been used as an inclusion criterion in two open and one closed clinical trials involving neuroblastoma of the central nervous system." (PMID 38925618, 2024). "In a study, YAP‐1 expression was investigated together with many genes in a retrospective cohort of 46 primary pediatric neuroblastoma patients, 30 of which were treatment‐refractory and 16 of which were after chemotherapy." (PMID 38925618, 2024). "YAP1 expression has been reported to significantly increase cell proliferation and growth through inhibition of 27Kip1 activity in neuroblastoma cell lines SH-SY5Y and SK-N-SH." (PMID 36121500, 2022). "We expressed Tead1-flag or Tead2-flag with either HA-tagged Yap1 or HA-tagged Taz in neuroblastoma cells (N2A) and performed co-immunoprecipitation experiments." (PMID 32170161, 2020). "The YAP1-mediated plastic switch towards a mesenchymal expression state in neuroblastoma cells may provide the molecular basis for novel therapeutic avenues." (PMID 41681855, 2026). "Here we explored the role of YAP1 in neuroblastoma aggressiveness and response to therapy." (PMID 41681855, 2026). "Data from cell models were compared with our published YAP1 expression data from neuroblastomas." (PMID 41681855, 2026). "Interestingly, YAP1 is part of the genetic signature that discriminates between mesenchymal and adrenergic differentiation states in neuroblastoma." (PMID 34503286, 2021). "ExomiR‐375 has been reported to promote bone marrow metastases in patients with neuroblastoma (NB) by downregulating YAP1 levels which enhance osteogenic differentiation of mesenchymal stromal cells." (PMID 36873941, 2023). "In conclusion, we identify a strong prognostic impact of neuroendocrine-lineage transcriptional profiles in neuroblastoma, and suggest that the evaluation of NOTCH1, INSM1, YAP1, and NEUROD1 might help to further characterize the risk of relapse in neuroblastoma patients." (PMID 36121500, 2022).
prostate tumors (13 papers, 2017 to 2025). "We observed that AR gene level positively correlated with YAP1 gene level (r = 0.4959) in prostate tumors." (PMID 39149855, 2024). "We next investigated the correlation between ITGA1/ITGA2 and YAP1 expression in the human prostate tumors and observed significant positive correlation in multiple independent PCa cohorts." (PMID 38169150, 2024). "The study further revealed that YAP1 silencing attenuated cell growth and invasion in vitro and suppressed prostate tumor xenografts in vivo." (PMID 32293349, 2020). "It was also recently determined that ERG (and the common TMPRSS2-ERG rearrangement) activates the transcriptional program regulated by YAP1, and that prostate-specific activation of either ERG or YAP1 in mice induces similar transcriptional changes and results in age-related prostate tumors." (PMID 36979713, 2023). "It is worth noting that these TMPRSS2-ERG gene rearrangements activate the transcriptional program regulated by YAP1 and that prostate-specific activation of either ERG or YAP1 in mice induces similar transcriptional changes and results in age-related prostate tumors." (PMID 37446279, 2023). "When we analyzed NCBI GEO data set (GSE6919) of normal prostate tissues, prostate tumor tissues, and metastatic prostate tumor tissues in PCa patients, the mRNA expression of YAP1 was significantly increased in metastatic prostate tumor tissues compared to primary ones." (PMID 34743733, 2021). "It was also recently determined that ERG (and the common TMPRSS2–ERG fusion) activates the transcriptional program regulated by YAP1, and that prostate-specific activation of either ERG or YAP1 in mice induces similar transcriptional changes and results in age-related prostate tumors." (PMID 33297404, 2020). "Both transcriptional regulator ERG (ERG) and TEAD4 can interact with the YAP1 promoter and increase H3K9/14Ac acetylation which leads to increased YAP1 expression in prostate tumors." (PMID 31216773, 2019). "Altogether, these data suggest that YAP1 and TAZ contribute unique functions in mechanotransduction and that WSS-induced motility of prostate tumour cells requires YAP1." (PMID 28098159, 2017). "To model this transition in disease progression, we established primary prostate tumours in mice orthotopically transplanted with PC3 cells and assessed YAP1 expression in the primary tumour and lymph nodes." (PMID 28098159, 2017). "CD248-CreERT2 conditional Yap1 knockout mice and human-derived ECM-CAF co-implantation models provided additional support that selectively disabling YAP1 in ECM-CAFs can slow prostate tumor growth, reduce matrix stiffness, and enhance responses to anti–PD-1 therapy." (PMID 41514658, 2025). "Evidence on YAP1 expression in human tissues is limited; however, the rate of strong nucleus-localized YAP1 staining in resistant tumors was significantly higher than that in naive tumors in the TMA study containing naive (hormone-responsive) and castration-resistant prostate tumors." (PMID 32293349, 2020).
rhabdomyosarcoma (13 papers, 2015 to 2024). A rare aggressive malignant mesenchymal neoplasm arising from skeletal muscle. "Finally, Vgll3 expression is 2.3-fold higher in mouse embryonal rhabdomyosarcomas caused by YAP1 S127A expression in activated satellite cells than in control skeletal muscle." (PMID 31138678, 2019). "Consistent with this, overexpression of constitutively active YAP1 S127A in activated satellite cells was sufficient to drive development of embryonal rhabdomyosarcomas in mice." (PMID 38183459, 2024). "In alveolar rhabdomyosarcoma associated with Pax3-FOXO1, RASSF4 is highly expressed and leads to YAP1 activation by the suppression of the Hippo pathway." (PMID 26690221, 2015). "More evidence of this positive feedback loop can be found in rhabdomyosarcomas, as the core Notch transcription RPBJ regulated YAP1 through direct transcription, and NICD overexpression increased YAP1 levels." (PMID 34797839, 2021). "Only 2 (CBEP3 and SATB1) out of 100 genes that are down regulated in YAP1 S127A and KRAS G12V-Cdkn2a-null induced rhabdomyosarcoma overlap with the bottom 100 genes whose low expression is best associated with poor survival in 18,000 cases of human cancer." (PMID 30353028, 2018). "Another example of signaling crosstalk identified by this analysis is that of YAP1_CTNNB1 interactions in L363 myeloma cells (94%ile), CADO-ES1 Ewing’s sarcoma cells (96%ile), and A204 rhabdomyosarcoma cells (96%ile)." (PMID 28118365, 2017). "In contrast, there is no overlap between genes that are repressed in both YAP1 S127A and KRAS G12V-Cdkn2a null-induced rhabdomyosarcoma, and genes that are significantly mutated in cancer." (PMID 30353028, 2018).
thyroid cancer (13 papers, 2014 to 2024). "We performed YAP1 staining in tissue microarrays of human thyroid cancers: 80% of patient samples with BRAF mutations and 60% with RAS mutations had NU-YAP." (PMID 36476495, 2022). "A recent study demostrated that FRMD6 had a tumor suppressor role by suppressing the activation of carcinogenic YAP1 in thyroid cancer." (PMID 37215455, 2023). "Collectively, these data suggest that up-regulation of LETM1 induces sustained activation of proliferative signaling pathways, such as PDGF signal pathway by AKT induced YAP1 transactivation, resulting in aggressive thyroid cancer phenotypes." (PMID 27556512, 2016). "Increased expression of YAP1 has also been described in thyroid cancer tissues." (PMID 37383164, 2023). "Interestingly, the cell surface protein VASN has previously been implicated in the promotion of YAP1/TAZ and EMT activity in thyroid carcinomas." (PMID 37370765, 2023). "YAP1 can inhibit the AKT pathway and suppress the growth of thyroid carcinoma cells." (PMID 31179326, 2019).
brain tumors (12 papers, 2015 to 2024). "Loss of NF2 protein also leads to the elevation of Yap1, a downstream effector protein, and we visualized increased Yap1 using immunohistochemistry in both the primary brain tumor and its lung metastasis." (PMID 29764516, 2018). "YAP1 is widely expressed in human brain tumors and is strongly associated with poor survival." (PMID 38477830, 2024). "To identify tumor-specific candidate regulatory elements we performed pairwise comparisons between three different mouse brain tumors (YAP1-, PDGFB- and RELA-driven tumors) and normal mouse brains." (PMID 37739938, 2023). "Here we show that, ectopic expression of active nuclear YAP1 (nlsYAP5SA) in ventricular zone neural progenitor cells using conditionally-induced NEX/NeuroD6-Cre is sufficient to drive brain tumour formation in mice." (PMID 32404936, 2020). "The YAP1-MAMLD1 fusion was able to induce brain tumors in both prenatal and neonatal brains at varying efficacy." (PMID 33228790, 2020). "By contrast, no brain tumor formation was observed in the lentivirus injection with YAP1-MAMLD1 (without additional Cdkn2a loss), whereas small tumor or neoplastic lesions were detected upon additional co-injection of sgCdkn2a." (PMID 33228790, 2020). "Editors' choice: A new brain tumour model in zebrafish allows simultaneous analysis of malignant tumours and heterotopias, suggesting that both lesions originate from similar events, with Yap1 as a driving force in tumour development." (PMID 27935819, 2017). "Although it is generally accepted that YAP1 is the main functional output of the hippo pathway and that its dysregulation leads to tumourigenesis, it remains to be tested whether YAP1 has an essential role in Lats1/2-dependent brain tumour generation." (PMID 32404936, 2020). "YAP1 involvement in the progression of LGG to secondary GBM and its contribution to an aggressive brain tumour phenotype is increasingly established." (PMID 39718433, 2024).